LIPA (lipase A, lysosomal acid type)
Diseases named in the same sentence as LIPA in open-access papers (continued):
Sharing a sentence is not in itself a finding about the gene and the disease.
atherosclerosis (continued). "Subsequent reports indicated low levels of LIPA expression in mouse and human SMCs relative to macrophages and other tissues, but the functional significance of that in atherosclerosis was not explored." (PMID 36204319, 2022).
lysosomal acid lipase deficiency (20 papers, 2016 to 2026). "Lysosomal acid lipase deficiency (LAL-D) is a rare autosomal recessive lysosomal storage disorder caused by mutations in the LIPA gene." (PMID 40216942, 2025). "Lysosomal acid lipase deficiency (LAL-D) is an autosomal recessive disorder caused by mutations in the LIPA gene, which results in lipid accumulation leading to multi-organ failure." (PMID 40216942, 2025). "Lysosomal acid lipase deficiency (LAL‐D) is an autosomal recessive disorder that relates to a mutation of the LIPA gene." (PMID 31392116, 2019). "Two homozygous patients were found with the pathogenic LIPA variant, described previously as the most prevalent cause for lysosomal acid lipase deficiency (LAL-D), which could mimic FH and, thus, result in undertreatment and progressive liver failure." (PMID 39769230, 2024). "Lysosomal acid lipase deficiency caused by homozygous LIPA variants may have a variable clinical course, and in the later-onset subtype, it is commonly misdiagnosed as FH or a hepatic disease, such as metabolic dysfunction-associated steatotic liver disease." (PMID 39769230, 2024). "Lysosomal acid lipase deficiency (LAL-D) is an autosomal recessive genetic disease arising from mutations in the lipase A, lysosomal acid type (LIPA) gene, characterised by the formation of cholesterol esters and triglyceride storages, primarily in the liver and spleen." (PMID 39650963, 2024). "Finally, we observed one ClinVar pathogenic and one novel putative pathogenic variant in LIPA, both in heterozygous state, associated with lysosomal acid lipase deficiency." (PMID 36329474, 2022). "This study developed an AAV-based gene therapy for lysosomal acid lipase deficiency (LAL-D), a rare disorder that results from mutations in the lipase A (LIPA) gene." (PMID 36092360, 2022). "Laboratory diagnostics of lysosomal acid lipase deficiency (LAL‐D), a rare disorder associated with LIPA alterations, are based on the evaluation of LAL activity." (PMID 31392116, 2019). "We have found the unconjugated acid 3β,5α,6β-trihydroxycholan-24-oic acid to be elevated also in patients with the autosomal recessive lysosomal storage disorder, lysosomal acid lipase deficiency (LALD), caused by mutations in the LIPA (lysosomal acid lipase) gene." (PMID 31839688, 2019). "Lysosomal acid lipase deficiency (LALD, Online Mendelian Inheritance in Man number 278000) is a rare, autosomal recessive inborn error of lipid metabolism caused by biallelic pathogenic variants in the LIPA gene, which encodes the enzyme lysosomal acid lipase (LAL)." (PMID 32093730, 2020).
dyslipidemia (18 papers, 2005 to 2025). "A homozygous missense variant (NM_001127605.3:c.928T>A, p.Trp310Arg) of the LIPA gene which caused LAL-D was found to be associated with dyslipidemia, fatty liver disease and/or cirrhosis in six members of an Iranian family." (PMID 37543928, 2023). "We found a homozygous missense variant (NM_001127605.3:c.928T > A, p.Trp310Arg) of the LIPA genewhich caused LAL-D to be associated with dyslipidemia, fatty liver disease and/or cirrhosis in six members of a family." (PMID 37543928, 2023). "Due to the association between lipidemia and LAL-D, subsequent studies have been designed to identify LIPA variants in dyslipidemia." (PMID 36555187, 2022). "In conclusion, the rs1051338 polymorphism of the LIPA gene influences the lipid profile contributing to worse a form of dyslipidemia LAL‐D‐like and was significantly associated to a worse hepatic steatosis in subjects with NAFLD." (PMID 34476902, 2021). "In this study, the association between the rs1051338 SNP in the LIPA gene and hepatic steatosis was evaluated in patients with atherogenic dyslipidemia and NAFLD." (PMID 34476902, 2021). "The untreated lipoprotein profile of our CESD patient revealed not only a combined hypercholesterolemia and hypertriglyceridemia, but also a severe hypoalphalipoproteinemia, indicating that mutations in LIPA are a rare genetic cause of complex dyslipidemia." (PMID 16255772, 2005). "Moreover, the rs1051338 polymorphism in LIPA gene has been previously associated by disequilibrium linkage to increased risk of atherogenic dyslipidemia, metabolic syndrome, obesity, and cardiovascular disease." (PMID 34476902, 2021). "A common polymorphic variant(rs1051338) in LIPA gene has been associated to atherogenic dyslipidemia,metabolic syndrome, obesity, and cardiovascular disease and, in vitro, couldadversely affect the LAL activity." (PMID 34476902, 2021). "Indeed, liver-specific LIPA deficiency is associated with dyslipidemia and increased cholesteryl ester storage." (PMID 32093730, 2020). "Deficiency of LIPA causes dyslipidemia and liver dysfunction." (PMID 31331100, 2019). "Before an expanded NGS panel for dyslipidemia containing the LIPA gene was established, genetic testing was first performed to exclude FH, and therefore, genetic testing for LAL-D was performed later." (PMID 35903350, 2022). "In addition, variants in genes causing other dyslipidemias showing phenotypes overlapping with FH may mimic FH in patients without causative variants (FH-phenocopies; ABCG5, ABCG8, CYP27A1 and LIPA genes) or act as phenotype modifiers in patients with a pathogenic variant in a causative gene." (PMID 36834635, 2023). "The LIPA gene is a biological candidate for CAD and dyslipidemia because it is involved in cholesteryl ester and triglyceride hydrolysis in lysosomes to generate free cholesterol and free fatty acids, and, consequently, plays a role in atherosclerotic plaque formation." (PMID 24069331, 2013).
fatty liver disease (15 papers, 2015 to 2025). A reversible condition wherein large vacuoles of triglyceride fat accumulate in liver cells via the process of steatosis. "This patient, a 37‐year‐old male with hyperferritinemia (318 ng/mL), hyperlipidemia (LDL 164 mg/dL), and hepatic steatosis, harboured a homozygous pathogenic splicing variant (NM_001127605.3: c.894G>A, p.Ser275_Gln298del) in LIPA gene." (PMID 39945383, 2025). "In this study, the homozygous missense variant (NM_001127605.3:c.928T > A, p.Trp310Arg) of LIPA which caused LAL-D was found to be associated with fatty liver disease and/or cirrhosis." (PMID 37543928, 2023). "Here, we describe a novel mutation in the LIPA gene associated with severe fatty liver disease and cirrhosis." (PMID 37543928, 2023). "Here, we report a novel missense variant (NM_001127605.3:c.928T>A, p.Trp310Arg) of LIPA in an Iranian family with fatty liver disease identified by whole-exome sequencing and confirmed by Sanger sequencing." (PMID 37543928, 2023). "A homozygous missense variant (NM_001127605.3:c.928T>A, p.Trp310Arg) of LIPA which caused LAL-D was found to be associated with fatty liver disease and/or cirrhosis." (PMID 37543928, 2023). "Lysosomal acid lipase deficiency (LAL‐D) is an autosomal recessive disease characterized by hypoalphalipoproteinemia, mixed hyperlipemia, and fatty liver (FL) due to mutations in LIPAse A, lysosomal acid type (LIPA) gene." (PMID 34476902, 2021). "In the current study, the M1 cluster expressed metabolism-associated genes, such as CETP, LIPA, and APOE, suggesting that a potential interactant between M1 cluster and hepatic steatosis in ALC and HBV-related cirrhosis." (PMID 36817578, 2023). "One of the family members had fatty liver without the missense variant of LIPA, he was obese and had a BMI of 31.14 kg/m2." (PMID 37543928, 2023). "Based on available data, all patients with LIPA gene disorders have liver steatosis." (PMID 26602919, 2015).
Hypercholesterolemia (13 papers, 2005 to 2025). An increased concentration of cholesterol in the blood. "It is likely that heterozygous substitutions in LIPA can lead to lipase A deficiency and cause hypercholesterolemia." (PMID 31795497, 2019). "A splice site mutation of the LIPA gene (c.894G > A) was reported to be producing the hypercholesterolemia phenotype with elevated total cholesterol and LDL-C levels." (PMID 28577571, 2017). "Indeed, lysosomal acid lipase (LIPA) has been linked to hypercholesterolemia, whilst ABO and serologically defined colon cancer antigen 8 (SDCCAG8) have been identified as genes underlying the development of CHD and diastolic blood pressure, respectively." (PMID 40076974, 2025). "Moreover, individuals heterozygous for the E8SJM LIPA mutations were found to have altered lipid profiles with a polygenic hypercholesterolemia phenotype, leading to an increase in cardiovascular risk profile." (PMID 24069331, 2013). "LIPA is a very important hydrolase, and reducing its activity can lead to symptoms such as hypercholesterolemia and hepatomegaly." (PMID 37510289, 2023). "We found that mutations in lipase A (LIPA) and lipoprotein lipase (LPL) cause symptoms such as nodular changes affecting the eyelids, hypercholesterolemia, hepatosplenomegaly and xanthomatosis." (PMID 26055101, 2015). "Additionally, rare variants in LDLRAP1, LIPA, and ABCG5/8 cause a purely autosomal recessive hypercholesterolemia, in which recessive forms have hypercholesterolemia phenotypically similar to FH." (PMID 30526649, 2018).
coronary artery disease (12 papers, 2013 to 2025). "Beyond clinical endpoints, we also found a significant association between genetically proxied monocyte LIPA expression and carotid plaque as captured by ultrasound, as well as myocardial infarction, ischemic heart disease, and coronary atherosclerosis." (PMID 40555237, 2025). "Surprisingly, the coronary artery disease variants are associated with increased LIPA expression in some cell types." (PMID 28279971, 2017). "This study identifies a coding variant in LIPA as likely causal variant at the 10q23 coronary artery disease–associated locus." (PMID 28279971, 2017). "The lysosomal acid lipase A (LIPA) gene has been identified as a susceptibility gene for coronary artery disease by several genome-wide association studies." (PMID 25699256, 2015). "Four gene variants related to lipid metabolism (including the rs562338 and rs503662 variants of the APOB gene, the rs7767084 variant of the LPA gene and the rs2246942 variant of the LIPA gene) have been shown to be associated with coronary heart disease (CHD)." (PMID 23653095, 2013). "Interestingly, genome‐wide association studies and functional genomic studies have identified LIPA as a risk locus for coronary heart disease in humans, but the causal variants and mechanisms remain to be determined." (PMID 40859629, 2025). "Additionally, the gene encoding for LAL (LIPA) was identified as a susceptibility gene for coronary artery disease by several genome-wide association studies." (PMID 33855029, 2021). "The rs1412444 and rs2246833 polymorphisms within the LIPA gene were recently found to be significantly associated with coronary artery disease (CAD) in genome-wide association studies in Caucasian and Asian populations." (PMID 24069331, 2013). "Bioinformatic studies identified that LIPA is correlated with coronary heart disease." (PMID 33613306, 2021).
steatosis (12 papers, 2012 to 2025). Increased lipid within the cytoplasm of cells. "We identified the steatosis-associated changes in the regulation of LIPA activity based on the alteration in its intracellular distribution, and we proposed the mechanism by which it can contribute to the establishment of hepatic IR." (PMID 21904679, 2012). "In the present study, we provide evidence that in steatosis the increased degradation of TAG mediated by LIPA and associated with the increased production of DAG may be one of the mechanisms determining the rapid onset of hepatic IR." (PMID 21904679, 2012). "Importantly, we found that lysosomal DEPs, including CTSB/D/Z, LIPA, DPP7 and GLMP, and mitocondrial DEPs, AKR1B10, and VAT1 had been connected with liver fibrosis, damage, and steatosis in previous studies, validiting our dataset." (PMID 34440927, 2021). "Importantly, we found that a subset of those proteins, CTSB, LIPA, DPP7, and GLMP had been previously connected with liver fibrosis, liver damage, and steatosis." (PMID 34440927, 2021). "Interestingly, lysosomal proteins such as cathepsin B (CTSB), lysosomal acid lipase (LIPA), dipeptidyl peptidase 2 (DPP), and glycosylated lysosomal membrane protein (GLMP), which are known to be involved in liver fibrosis, liver damage, and steatosis, were found to be differentially expressed." (PMID 34440927, 2021).
Obesity (10 papers, 2019 to 2025). Accumulation of substantial excess body fat. "Lysosomal lipase (LIPA/LAL) deficiency (LAL-D) is another example of hepatic lysosomal dysfunction associated with obesity." (PMID 31357643, 2019). "Furthermore, adipocyte LIPA deficiency impaired thermogenesis and oxygen consumption and rendered mice susceptible to diet-induced obesity." (PMID 40091840, 2025). "Adipocyte LIPA deficiency mediates the development of obesity and associated glucose intolerance." (PMID 40091840, 2025). "The positive correlation of LIPA expression with obesity led us to first evaluate the baseline features of adipose tissue from ND-fed A-Lipa KO mice." (PMID 40091840, 2025). "The summation of these phenotypes highlights an essential role for adipocyte LIPA in mediating obesity-related TG storage, lipolysis, and metabolic outcomes." (PMID 40091840, 2025). "Other genes within the magenta module play a role in metabolic functions and obesity including genes that code for lipase (LIPA), phospholipid transfer protein (PTLP), and lipid metabolism (e.g., LPIN1)." (PMID 32151267, 2020). "Given that monocytes and macrophages express lysosomal genes including LIPA and are recruited into adipose tissue in response to metabolic stressors such as cold and obesity, we evaluated the contribution of macrophages to adipose tissue LIPA expression with fasting or CE." (PMID 40091840, 2025).
hyperlipidemia (9 papers, 2016 to 2025). "Second, alternative causes of hyperlipidemia should be considered—four unique P and LP variants in other genes (CYP27A1, ABCG5, ABCG8, and LIPA) were found in seven patients (2% of all patients with positive monogenic variant), which increases the overall diagnostic yield to 23.6%." (PMID 39769230, 2024). "On the other hand, other interesting genes, not responsible for FH but associated with hyperlipidemia (such as APOE and LIPA), have been identified." (PMID 33137929, 2020).
melanoma (8 papers, 2016 to 2024). A malignant, usually aggressive tumor composed of atypical, neoplastic melanocytes. "In melanoma, exosomal hsa-miR-125-5p was found to influence tumor-associated macrophages and, potentially via targeting of lysosomal acid lipase A (LIPA), helps in macrophage polarization to a tumor-promoting phenotype." (PMID 34067485, 2021). "We showed that the expression of lipid metabolism-associated genes, including LIPA, were strongly decreased in M1 macrophages previously treated with melanoma-derived exosomes." (PMID 32079286, 2020). "Correspondingly, LIPA knockout in melanoma-associated myeloid cells promotes cancer cell proliferation and metastasis." (PMID 32079286, 2020). "From all the putative targets of miR-125b-5p, we identified LIPA as the most abundant and strongly decreased transcript following treatment of M1 macrophages with melanoma-derived exosomes." (PMID 32079286, 2020). "As miR-125b-5p has been demonstrated to bind directly to the LIPA 3’UTR, our data indicates that melanoma exosome-delivered miR-125b-5p directly targets LIPA in TAMs, which in turn induces a proinflammatory and tumor-permissive phenotype." (PMID 32079286, 2020). "DNA methylation master regulator UHRF1 and DNA methyltransferase inhibitor zebularine may upregulate LIPA in mesothelioma cells and mouse melanoma, respectively, and histone deacetylase inhibitor voronistat increases LAL protein and activity in fibroblasts." (PMID 36204319, 2022).
lung carcinoma (4 papers, 2011 to 2024). "The expression of SCGB1D1 (LIPA), SCGB2A1 (MGB2), and SCGB2A2 (MGB1) has been shown to be upregulated in human lung cancers." (PMID 21385388, 2011).
cryptogenic cirrhosis (3 papers, 2015 to 2022). "We aimed to determine LAL-activity, and to investigate the most common single nucleotide polymorphism (SNP) affecting the LIPA gene and responsible for 50–70% of LAL-d cases (rs116928232 c.894G>A), in patients with cryptogenic cirrhosis." (PMID 27219619, 2016). "Our results demonstrate that the DBS-determined LAL activity is severely reduced in patients with cryptogenic cirrhosis and that this reduction is not secondary to the inclusion of any subject carrying the E8SJM mutation in the LIPA gene either at the homozygous or at the heterozygous level." (PMID 27219619, 2016).
breast carcinoma (2 papers, 2022 to 2024). "Furthermore, single-cell profiling of myeloid cells from patients with breast cancer identified lipid-associated macrophages that co-expressed the TTR macrophage markers CD63, LIPA, GPNMB, MCR1, CD163, and MSR1." (PMID 38942020, 2024).
lipid metabolism disorders (2 papers, 2021 to 2025). "Depletion of LIPA causes lipid metabolism disorders in mice." (PMID 33613306, 2021).
malaria (2 papers, 2013 to 2021). Malaria is a serious and sometimes fatal disease caused by a parasite that commonly infects a certain type of mosquito which feeds on humans. "Since components of the FASII pathway and subunits of the PDH complex (albeit not the lipoylated E2 subunit) have been successfully deleted in blood stage malaria parasites, LipA is presumed to be similarly dispensable and not required for apicoplast maintenance." (PMID 24086138, 2013).
myocardial infarction (2 papers, 2025). Gross necrosis of the myocardium, as a result of interruption of the blood supply to the area, as in coronary thrombosis. "After Bonferroni correction, the results revealed that, with the exception of the FAM13B gene (no corresponding data available) and the LIPA gene (unstable causal relationship with MI), the remaining 11 genes all demonstrated a causal relationship with myocardial infarction." (PMID 41004172, 2025).
non-alcoholic fatty liver disease (2 papers, 2017 to 2024). "Additionally, CYP2R1 and DHCR7 are related to vitamin D metabolism, LIPA is associated with non-alcoholic fatty liver disease, and CYP21A1 affects animal development." (PMID 39376613, 2024).
sitosterolemia (2 papers, 2022 to 2024). A rare autosomal recessive sterol storage disease characterized by the accumulation of phytosterols in the blood and tissues. "Finally, phenocopies of FH may occur due to defects in ABCG5/ABCG8 (sitosterolemia) and LIPA (lysosomal acid lipase)." (PMID 36431115, 2022).
Stroke (2 papers, 2017 to 2020). Sudden impairment of blood flow to a part of the brain due to occlusion or rupture of an artery to the brain. "We identified colocalization signals at several established single trait loci such as TCF21, ADAMTS7, and LIPA for CAD, and NGF, FHL5, TSPAN2, and SLC24A3 for stroke." (PMID 31917787, 2020).